CLDN4 (claudin 4)
Diseases named in the same sentence as CLDN4 in open-access papers (continued):
Sharing a sentence is not in itself a finding about the gene and the disease.
bladder tumor (2 papers, 2022 to 2023). "Interestingly, differential CLDN4 expression reported as CLDN4 overexpression in differentiated carcinomas compared to the downregulation in invasive/high-grade bladder tumors was associated with a low versus high level of CLDN4 methylation, respectively." (PMID 36672179, 2023).
bladder urothelial carcinoma (2 papers, 2022 to 2024). "The tight junction (TJ) protein claudin-4 (CLDN4) is overexpressed in bladder urothelial carcinoma (BUC) and correlates with cancer progression." (PMID 35742959, 2022). "CLDN4 is also a tumor promoter gene in urothelial bladder cancer." (PMID 38731853, 2024).
carcinoma in situ (2 papers, 2013 to 2023). "Another important finding was that claudin-4 expression was maintained through the progression to atypical lesions and in situ carcinomas, thus resulting in a larger contingent of positive samples in our series and therefore lacking correlation with morphological or radiological categories." (PMID 23657508, 2013).
cholangiocarcinoma (2 papers, 2012 to 2025). A carcinoma that arises from the intrahepatic biliary tree (intrahepatic cholangiocarcinoma) or from the junction, or adjacent to the junction, of the right and left hepatic ducts (hilar cholangiocarcinoma). "In cholangial carcinoma (CCAS), increased expression of CLDN4 was observed in hyperplastic/dysplastic biliary epithelia and cholangiocarcinoma (CCA), indicating a potential role in early carcinogenesis." (PMID 40687428, 2025).
cryptococcal infection (2 papers, 2021 to 2023). "In contrast, we found that the expression of claudin-4 was higher in clinical specimens from patients with cryptococcal infection than in normal specimens." (PMID 37186068, 2023). "In contrast, the expression of claudin-4 in clinical specimens from patients with cryptococcal infection was higher than that in normal specimens." (PMID 37186068, 2023). "After cryptococcal infection, mouse body weights were not lower in Cldn-4−/− mice compared with Cldn-4+/+ mice." (PMID 34702961, 2021).
ductal carcinoma (2 papers, 2005 to 2025). "They reported that CLDN4 and E-cadherin accurately predicted relapse-free survival in a validation cohort at five years, with efficacy across luminal and ductal carcinomas." (PMID 40487255, 2025).
epithelioid mesothelioma (2 papers, 2018 to 2023). "In the differential diagnosis between sarcomatoid carcinoma (SC) and sarcomatoid mesothelioma (SM), we aimed to investigate the role of Claudin-4 and BAP1, a panel recently used to distinguish conventional carcinoma from epithelioid mesothelioma." (PMID 36673059, 2023). "CEA and Claudin 4 expressions were not present in any of the epithelioid mesotheliomas." (PMID 29317712, 2018).
glioblastoma (2 papers, 2024 to 2026). The most malignant astrocytic tumor (WHO grade IV). "Simultaneously, TGF‐β could induce glioblastoma mesenchymal transition through upregulation of CLDN4 and nuclear translocation to activate TNF‐α/Nuclear Factor Kappa‐B (NF‐κB) signal pathway." (PMID 38629624, 2024).
gynecologic cancers (2 papers, 2020 to 2025). "A tissue microarray of primary tumors from SCCOHT and other gynecological cancers were stained for Claudin-4 and CD44." (PMID 33355532, 2020).
hydronephrosis (2 papers, 2012 to 2019). Collection of urine in the renal pelvis that results in dilatation of the renal pelvis and calyces. "In the current study, we developed Cldn4−/− mice and found that Cldn4 deficiency also resulted in the development of hydronephrosis." (PMID 23284964, 2012). "While most of the hydronephrosis was observed unilaterally before 15 months, the proportion of bilateral hydronephrosis was markedly increased after 16 months Cldn4−/− mice, leading to increased mortality." (PMID 23284964, 2012). "Random sampling autopsy indicated that the macroscopic hydronephrosis was already evident in 54% of Cldn4−/− mice before 10 months of age and in 83% after 16 months." (PMID 23284964, 2012). "IVP examination indicated that the urinary flow was retarded to variable extents in Cldn4−/− mice prior to the overt development of hydronephrosis." (PMID 23284964, 2012). "The results suggested urinary tract obstruction in Cldn4−/− mice prior to hydronephrosis and prompted us to carefully examine the histology of the urothelium." (PMID 23284964, 2012). "It was found that the urothelial layers of the renal pelvic region and ureters were thickened diffusely with markedly increased cellularity and layers in Cldn4−/− mice prior to the development of hydronephrosis." (PMID 23284964, 2012). "In conclusion, we have demonstrated that Cldn4−/− mice develop chronic urothelial hyperplasia and eventually overt hydronephrosis." (PMID 23284964, 2012). "We generated Cldn4−/− mice and found that these mice had increased mortality due to hydronephrosis of relatively late onset." (PMID 23284964, 2012). "In current study, we demonstrate that Cldn4−/− mice develop progressive hydronephrosis as they age, resulting in increased mortality." (PMID 23284964, 2012). "Prior to overt hydronephrosis, 3-month-old Cldn4−/− mice showed serum blood urea nitrogen and creatinine within normal ranges." (PMID 23284964, 2012). "Cldn4−/− mice over 1 year of age frequently showed striking hydronephrosis with markedly dilated pelvis and severely compressed renal parenchyma." (PMID 23284964, 2012). "Prior to the development of overt hydronephrosis, Cldn4−/− mice showed diffuse hyperplasia and thickening of the urothelium leading to urinary tract obstruction as revealed by intravenous pyelography (IVP), while the structure of TJs and the gross barrier effect were largely retained." (PMID 23284964, 2012). "The hydronephrosis developed unilaterally with no overt clinical signs, but the disease progressed bilaterally in a significant proportion of Cldn4−/− mice with age, causing increased mortality." (PMID 23284964, 2012). "Although BrdU staining was rarely observed in the urothelial cells in Cldn4+/− mice, both the pelvic and ureteral urothelial cells of Cldn4−/− mice with no overt hydronephrosis showed significant incorporation of BrdU." (PMID 23284964, 2012). "None of the Cldn4+/− littermates developed hydronephrosis until 21 months of age." (PMID 23284964, 2012). "Relatively late onset and chronic progression of hydronephrosis in Cldn4−/− mice, as opposed to early and rapid progression in UP−/− mice, may be due in part to the compensatory function of Cld7 at TJs." (PMID 23284964, 2012).
injury (2 papers, 2018 to 2022). Damage inflicted on the body as the direct or indirect result of an external force, with or without disruption of structural continuity. "Alterations in expression of the tight junction genes claudin-3 and claudin-4 occurs within 3 days of IR in parotid glands, and increased claudin-4 expression accompanies acute lung injury." (PMID 36263624, 2022). "The expressions of the majority of claudin isoforms (CLDN1, 2, 5, 10, 11, 14, 19, 20, and 22) were decreased after nerve injury while the expressions of a few isoforms (CLDN4, 15, and 23) were increased." (PMID 30425652, 2018).
kidney cancer (2 papers, 2017 to 2022). Primary or metastatic malignant neoplasm involving the kidney. "In kidney cancer, the nuclear accumulation of CLDN4 promotes the malignant progression of tumors and induces EMT." (PMID 35418179, 2022). "Previous studies have demonstrated that the nuclear accumulation of CLDN4 promotes the malignant progression of kidney cancer and EMT." (PMID 35418179, 2022).
liver cancer (2 papers, 2021 to 2023). An epithelial or non-epithelial malignant neoplasm that arises from the liver. "Furthermore, even in liver cancer with a low level of CLDN4 expression, CLDN4 expression is increased in liver cirrhosis compared to normal liver tissue." (PMID 36982569, 2023).
lung fibrosis (2 papers, 2023 to 2024). "During the period of lung fibrosis, several intermediate AECII was detected by specific markers such as keratin 8 (KRT8), claudin 4 (CLDN4) and stratifin (SFN)." (PMID 37161570, 2023).
Lymphatic Metastasis (2 papers, 2021 to 2023). Transfer of a neoplasm from its primary site to lymph nodes or to distant parts of the body by way of the lymphatic system. "Multivariate COX regression analysis showed that CTC counts (HR = 1.3, p < 0.001), Claudin-4 (HR = 4.6, p = 0.008), and Lymphatic metastasis (HR = 12.9, p = 0.001) were independent factors for poor prognosis." (PMID 37465316, 2023). "Several reports indicated a positive protein expression of CLDN-4 connected to poor prognosis, advanced grade, and lymphatic metastasis of BrCa." (PMID 33407452, 2021).
malignant melanoma (2 papers, 2017 to 2018). "The activation transcription factors, which regulate SPRR1A (small proline rich protein 1A), KRT78, claudin 4 and RAB25 (a member of the RAS oncogene family), also play crucial roles in malignant melanoma metastasis." (PMID 29377892, 2018).
mastitis (2 papers, 2025 to 2026). Inflammation of breast tissue during lactation or postpartum due to an obstructed duct or infection. "Lipopolysaccharide-induced mastitis disrupts the blood-milk barrier by altering claudin composition (e.g. claudin-3 phosphorylation and claudin-4/7 recruitment) in mammary alveolar tight junctions, facilitating the influx of neutrophils and red blood cells into mammary acini." (PMID 41343264, 2025).
medullary carcinomas (2 papers, 2014 to 2024). "While those results align with ours, the authors reported that claudin-4 was expressed in ~40% of medullary carcinomas." (PMID 39458944, 2024). "Only one patient was positive for CLDN1, CLDN2, and CLDN7 expression, and two of three patients with medullary carcinomas were positive for CLDN4 expression." (PMID 25393310, 2014). "All medullary carcinoma samples were negative for claudin-4 expression." (PMID 39458944, 2024).
necrotizing enterocolitis (2 papers, 2020 to 2022). Necrotizing enterocolitis (NEC) is a devastating disease that affects mostly the intestine of premature infants. "It was previously reported that the intestinal TJ proteins, namely, ZO-1, Occludin, and Claudin-4, were significantly downregulated in necrotizing enterocolitis (NEC)." (PMID 33426071, 2020). "Furthermore, In a neonatal mouse necrotizing enterocolitis (NEC) model, B. infantis modulates the proper localization of claudin 4 and occludin in TJs, attenuates intestinal permeability, protects intestinal barrier function, and reduces the incidence of NEC." (PMID 35910620, 2022).
oral cancer (2 papers, 2020). "Among the 57 cases of oral cancer examined in this study, intraoral CLDN4 was found in 22 (39%) of them." (PMID 32064037, 2020). "We previously reported that nuclear CLDN4 is correlated with the activation of YAP in oral cancer." (PMID 33172177, 2020). "In our previous study, intranuclear CLDN4 was observed in approximately 30% of oral cancer cases." (PMID 33172177, 2020). "Previous reports have suggested that CLDN4 is expressed at low levels in RCC and in the bladder, colon, stomach, pancreatic, breast, and oral cancers." (PMID 33172177, 2020).
pancreatic adenocarcinoma (2 papers, 2017 to 2020). "Claudin-4 was found to be expressed in 7 of 8 cell lines, with the highest levels in the human pancreatic adenocarcinoma Capan-2 cells and the lowest in the human pancreatic epithelial carcinoma Mia-PaCa-2 cells." (PMID 32414951, 2020).
reflux esophagitis (2 papers, 2020 to 2025). "In reflux esophagitis, Nrf2 binds directly to the claudin-4 promoter, enhancing its expression, whereas Nrf2 deficiency results in mitochondrial dysfunction, reduced claudin-4 levels, and impaired junctional integrity." (PMID 41462607, 2025).
Sepsis (2 papers, 2023). Sepsis is defined as life-threatening organ dysfunction caused by a dysregulated host response to infection. "In a study investigating the impact of berberine pretreatment on sepsis, occludin, ZO-1, and claudin-4 were found to exhibit decreased expression levels following CLP in rats." (PMID 38187112, 2023). "However, the expression of alveolar epithelial claudin-4 is downregulated in sepsis, which increases the severity of lung injury." (PMID 37186068, 2023).
soft tissue neoplasm (2 papers, 2017 to 2022). A benign, intermediate, or malignant neoplasm that arises from the soft tissue. "In order to compared the performance of FDCSP and SRGN with known FDC-S markers in the differential with soft tissue tumors, we tested CD21, CD23, CD35, CXCL13, Clusterin, Claudin 4 and Podoplanin in our groups of tumors and controls." (PMID 28145886, 2017).
urothelial carcinoma (2 papers, 2019 to 2025). A malignant neoplasm derived from the transitional epithelium of the urinary tract (urinary bladder, ureter, urethra, or renal pelvis). "Additionally, we observed the overexpression of MUC4, a transmembrane mucin associated with metastatic urothelial carcinoma, and CLDN4, a marker linked to more invasive and higher-grade urothelial carcinomas." (PMID 40004083, 2025).
uterine cancer (2 papers, 2011 to 2018). Primary or metastatic malignant neoplasm involving the uterine corpus and/or the cervix. "Conversely, claudin-4 overexpression has been positively correlated with increased invasiveness, metastasis, angiogenesis and poor prognosis in several other cancer types, including breast, gastric, lung, ovarian, prostate and uterine cancers." (PMID 28842811, 2018).
Williams-Beuren syndrome (2 papers, 2020 to 2025). "CLDN4 gene is removed in the Williams-Beuren syndrome, and its abnormal expression is observed in several malignancies." (PMID 33282635, 2020).
adenosis (1 paper, 2013). "Claudin-4 expression, for instance, was negative in 17 cases of non-malignant breast lesions, especially those harboring apocrine metaplasia and adenosis." (PMID 23657508, 2013). "By observing the scope of different alterations on the benign diagnostic samples, we could see that apocrine metaplasia was almost always totally negative for claudin-4 and extended areas of adenosis were usually negative." (PMID 23657508, 2013).
Alzheimer disease (1 paper, 2020). A progressive, neurodegenerative disease characterized by loss of function and death of nerve cells in several areas of the brain leading to loss of cognitive function such as memory and language. "The next step would be to examine astrocytic CLDN4 expression in other pathologies of the CNS, notably Alzheimer’s disease, stroke, or amyotrophic lateral sclerosis in which BBB permeability has been identified as a critical pathophysiological player." (PMID 33253145, 2020).
apocrine carcinomas (1 paper, 2020). "The finding is also consistent with the reported presence of an inverse relationship between claudin 4 and androgen receptor expression, as apocrine carcinomas are usually androgen receptor positive." (PMID 31044387, 2020).
Atrophy (1 paper, 2022). Any weakening or degeneration, especially through lack of use. "As expected, 90.9% of open-type atrophy was observed in the CLDN-4 high-expression group, whereas only 60.0% of the low-expression group showed the open type (p = 0.011)." (PMID 35743616, 2022). "Thus, we further investigated the relationship between CLDN-4 expression and a range of atrophy." (PMID 35743616, 2022).
Barrett’s esophagus (1 paper, 2023). Esophageal lesion lined with columnar metaplastic epithelium which is flat or villiform. "The same study also reported that most esophageal adenocarcinoma cases and its metastases exhibited a similar reaction pattern of claudin-4 to the one seen in Barrett’s esophagus." (PMID 37627123, 2023).
Barrett’s oesophagus (1 paper, 2023). "Moreover, the expression of CLDN3 and CLDN4 was significantly elevated both in Barrett’s oesophagus and OAC in comparison to the foveolar epithelium, while in OAC, the expression of CLDN2 was significantly higher in comparison to that in Barrett’s oesophagus." (PMID 38201579, 2023).
bile reflux (1 paper, 2023). "At present, several factors including H.Pylori (Hp), flora imbalance, inflammatory factors, genetic variations, Claudin-4, gastric stem cells, solute carrier family member 26 (SLC26A9), bile reflux, exosomes, and miR-30a plays a considerable role in the transformation of GPL into GC." (PMID 37719006, 2023).
bullous disorder (1 paper, 2023). "A noteworthy contribution of our study is the first-time report of claudin-4 overexpression in the keratinocytes surrounding blisters in an autoimmune-mediated subepidermal bullous disorder, bullous pemphigoid." (PMID 38534263, 2023).
bullous pemphigoid (1 paper, 2023). Bullous pemphigoid (BP) is the most common form of autoimmune bullous dermatosis. "Further, claudin-4 exhibited moderate-to-strong membranous staining in disrupted keratinocytes surrounding and within the acantholytic and bullous areas in 16/22 of the acantholytic cases (not seen in the six cases of mucosal PV) and all three bullous pemphigoids." (PMID 38534263, 2023).
cervical cancer (1 paper, 2014). A primary or metastatic malignant neoplasm involving the cervix. "We reported previously that knockdown of claudin-4 (CLDN4) in a human cervical cancer cell line 2008 markedly increases the growth of its xenografts and enhances their metastatic potential through down-regulation of E-cadherin mRNA and protein levels." (PMID 25344320, 2014). "We previously discovered that CLDN4 has quite marked effects on tumor growth rate and metastatic potential in the human cervical carcinoma cell line 2008." (PMID 25344320, 2014). "In a previous study we molecularly engineered the cervical carcinoma 2008 cell line to create a CLDN4KD subline in which the expression of CLDN4 was constitutively knocked down as a result of infection with a lentivirus expressing an shRNAi targeted to the CLDN4 mRNA." (PMID 25344320, 2014).
chromophobe renal cell carcinoma (1 paper, 2021). Chromophobe renal cell carcinoma is a rare subtype of renal cell carcinoma, originating from the intercalating cells of the collecting ducts and macroscopically manifesting as a well-circumscribed, highly lobulated, solid tumor that is usually diagnosed at an early stage. "There is growing evidence that Claudin 4 (CLDN4) plays a significant role in the occurrence and development of chromophobe renal cell carcinoma and could serve as an independent risk biomarker for the overall survival in patients with chromophobe renal cell carcinoma." (PMID 33686949, 2021).
Clostridium perfringens infection (1 paper, 2020). "In these cases, Clostridium perfringens infection was detected to impair tight junction through CPE, which led to the intracytoplasmic translocation of CLDN4 in these tumors." (PMID 33172177, 2020).
colonic adenomas (1 paper, 2018). "Here, we found that CLDN4 is expressed in colonic adenomas and adenocarcinomas." (PMID 30647838, 2018).
colorectal tumors (1 paper, 2023). "It was demonstrated that the aberrant expression of CLDN2, CLDN4, CLDN5, CLDN7, and CLDN23 are associated with the clinical value in colorectal tumors." (PMID 37799140, 2023).
Constipation (1 paper, 2024). Infrequent or difficult evacuation of feces. "The expression levels of three TJ components, including occludin, ZO-1, and claudin-1, except claudin-4, were significantly recovered in the Lop-induced constipation rat model after treatment with phlorotannin (Pt)." (PMID 39857371, 2024).
cyst (1 paper, 2022). A sac-like closed membranous structure that may be empty or contain fluid or amorphous material. "The loss of claudin-4 seen in RCs and DCs may reflect their role in cyst growth." (PMID 34808689, 2022). "The expression of claudin-4 in every cyst type was lower than that of claudin-1." (PMID 34808689, 2022).